LEP (leptin)
Diseases named in the same sentence as LEP in open-access papers (continued):
Sharing a sentence is not in itself a finding about the gene and the disease.
Insulin resistance (continued). "Risperidone could reduce both leptin-induced signal transducer and activator of transcription 3 (STAT3) phosphorylation and insulin-mediated protein kinase B activation, which could result in LEP and insulin resistance." (PMID 38375208, 2023). "Moreover, upregulation of serum adiponectin and downregulation of serum leptin concentrations after LPLM141 administration in HFD-fed rats might make contributions to alleviation of systemic inflammation and improvement of insulin resistance, respectively." (PMID 37114144, 2023). "Furthermore, they exhibited significantly elevated levels of serum leptin and RBP-4, along with decreased levels of serum adiponectin, which may indicate a potential link to insulin resistance." (PMID 37854195, 2023). "We hypothesized that the adiponectin–leptin ratio (AL ratio) could be a good marker for early detection of lean NAFLD independent of insulin resistance." (PMID 36790383, 2023). "The adiponectin/leptin ratio was suggested as an adipose tissue dysfunction marker and correlates with insulin resistance more closely than adiponectin or leptin alone, or even the HOMA-IR (homeostatic model assessment for insulin resistance) index which evaluates insulin resistance." (PMID 38136564, 2023). "However, due to the small size of the Study and Control Groups the role of diet in the treatment of insulin resistance in PCOS cannot be unequivocally stated; the same is true of the role of lifestyle intervention in modulating adiponectin, leptin and resistin concentrations." (PMID 37432289, 2023). "Leptin activates the renal sympathetic nerve and elevates arterial blood pressure, and adiponectin protects the heart and blood vessels and shows a negative correlation with insulin resistance." (PMID 36662790, 2023). "Thus, the improvements in muscle mass and contractile function by MEF‐secreted leptin are not mediated by reversal of the most likely systemic metabolic factors – insulin resistance, hyperlipidaemia and glucocorticoids." (PMID 35844058, 2022). "Leptin decreased (from 87.2 [48.6, 132.7] to 39.1 [21.0, 76.4] ng/ml) and adiponectin increased (from 5.6 [4.5, 7.5] to 7.1 [5.5, 8.5] μg/ml), with a reduction in LAR from 15 [8.4, 22.4] to 5.7 [3.0, 9.1] ng/μg (all p < 0.001), indicating decreased insulin resistance." (PMID 35662920, 2022). "Importantly, leptin supplementation prevents the appearance of insulin resistance and liver steatosis, but did not improve adipose tissue mass and quality." (PMID 35250856, 2022). "Limitations of our study include the lack of body composition and levels of AG and leptin assessments in the entire cohort, smaller sample size, sex imbalance, lack of pubertal stage data which may impact insulin resistance, and the cross-sectional design." (PMID 35456360, 2022). "We demonstrate that restoration of muscle mass and strength by adipose is separable from insulin resistance and other factors known to play a role in muscle pathology, indicating that a small amount of circulating leptin can maintain muscle mass and function independent of metabolic disturbance." (PMID 35844058, 2022). "This phenomenon could be explained by a variety of metabolic abnormalities including hyperinsulinemia, insulin resistance, increased insulin-like growth factor-1 (IGF-1) level, dyslipidemia, augmented inflammatory cytokines, elevated leptin, as well as decreased adiponectin." (PMID 36230836, 2022). "The excessive secretion of leptin and pro-inflammatory cytokines by adipose tissue as well as the prevailing state of insulin resistance in obese men exert a negative impact on the hypothalamic-pituitary-gonadal axis ultimately reducing the secretion of gonadotropins." (PMID 36686453, 2022). "Compared to healthy individuals, serum levels of both leptin and GAL were higher in obese children and the levels of GAL were positively correlated with the levels of fasting insulin, homeostasis model assessment-insulin resistance, triglycerides, and fasting glucose." (PMID 33802616, 2021).
Insulin resistance (continued). "The chronic inflammatory state observed in high adiposity, whether partially driven by leptin or not, seems to play a major role in the interplay between insulin resistance and hypertension." (PMID 34966295, 2021). "Physical exercise, in turn, moderates the inflammatory condition, decreasing the secretion of leptin and TNF-α, which is a metabolic cascade of changes in other adipokines, it reduces the secretion and cytokines of the insulin antagonist and subsequently improves insulin resistance." (PMID 34568974, 2021). "Secretion of adipokines (e.g. leptin) and cytokines (e.g. TNF-α, IL-6 and IL-1β), oxidative stress and, possibly, the gut microbiome contribute to pregnancy-induced insulin resistance, although understanding of pregnancy-induced insulin resistance is incomplete." (PMID 32556615, 2020). "However, they showed increased leptin sensitivity in the hypothalamus and did not develop diet-induced insulin resistance, suggesting that regulation of LepRb signaling by SOCS3 mediates diet-induced changes of glycemic control." (PMID 32731387, 2020). "Thus, it seems that the inability of the LAR method to detect the effect of fat distribution on insulin resistance (independent of total body fat and leptin) is an important disadvantage in predicting metabolic diseases." (PMID 33680012, 2020). "Furthermore, we show negative correlations between OB volume and insulin resistance, leptin levels and body fat." (PMID 33328935, 2020). "Although increased leptin, insulin and C-peptide levels may be involved in insulin resistance, increased adiposity and macrosomia, they were not significantly deviated from published data from other populations." (PMID 31975995, 2019). "The reasons for these gender differences are not known, but may relate to sex steroids, insulin resistance, and other hormones, such as leptin." (PMID 30626147, 2019). "Endoplasmic reticulum stress decreases or completely suppresses leptin signaling in obese humans with type 2 diabetes, suggesting that the negative effect of the endoplasmic reticulum on leptin sensitivity may also affect insulin resistance." (PMID 29498693, 2018). "Lastly, considering the epidemiologic feasibility, some other biochemical indexes that are reported to correlate with the presence of diabetes such as plasma insulin, estimated insulin resistance, plasma ghrelin, adiponectin, leptin and cytokines were not collected in our cross-sectional design." (PMID 30314516, 2018). "We hypothesized that leptin and osteocalcin would be negatively related to one another, and that leptin would be a negative predictor of serum glucose, insulin and insulin resistance." (PMID 28286536, 2017). "Visceral adiposity has been complicated with negative effects including insulin resistance and the elevated production of pro-inflammatory molecules leptin (LEP), resistin, tumor necrosis factor-α (TNF-α), IL-6, hypoxia-inducible factor 1 (HIF-1) and adipocyte fatty-acid binding protein (A-FABP)." (PMID 27703473, 2016). "The mechanisms by which leptin improves insulin resistance are not yet known." (PMID 26985241, 2016). "Increased TNF-α and leptin may also be predictive, but studies must firmly establish their role independent of BMI and insulin resistance." (PMID 26110385, 2015). "In addition, these inhibitors prevented the negative influence of PTP1B on leptin signaling pathways involved in the central regulation of energy expenditure and insulin resistance." (PMID 28031898, 2015). "Although the amount of leptin, fat mass, total cholesterol and triglycerides were increased in enalapril treated rats, we could not establish a correlation between insulin resistance and higher body mass in this study." (PMID 25926796, 2015). "Its effects on serum leptin levels and insulin resistance have not been studied yet." (PMID 26550014, 2015).
Insulin resistance (continued). "Considering insulin resistance is deeply associated with L-asp-related hyperglycemia, the limitation of this study is that we could not evaluate serum biomarker of insulin resistance such as leptin, adiponectin, GH and IGF1." (PMID 26317422, 2015). "As a result, leptin signaling abnormalities in the models may complicate their insulin resistance, which does not represent the human T2DM condition." (PMID 24809394, 2014). "Leptin and adiponectin were studied because of the evidence that leptin affected insulin resistance in mice independent of changing body weight, whereas adiponectin promoted the survival and function of islet β cells and improved peripheral insulin sensitivity." (PMID 24736781, 2014). "Epidemiological studies have suggested that leptin regulates total body sensitivity to insulin and triglyceride levels in leptin-deficient individuals, and there is a negative relationship between insulin resistance and cerebrospinal fluid leptin concentrations." (PMID 24809394, 2014). "Indeed, a study conducted in a group of obese adolescents revealed that high serum levels of leptin correlate with increased BMI and waist circumference, without having a significant relation with the insulin resistance level." (PMID 23986664, 2013). "However, in patients with lipodystrophy, a condition characterized by almost complete lack of adipose tissue, leptin levels are very low and correlate significantly with markers of insulin resistance." (PMID 24455420, 2013). "In the present study, we investigated how chronic exposure to increased leptin levels could modify the systemic cytokine profile and insulin resistance in a non-obese model." (PMID 23056516, 2012). "In leptin resistance, glucose-stimulated insulin secretion is not suppressed by leptin, which may lead to insulin resistance." (PMID 22533665, 2012). "These bioactive molecules, including leptin, adiponectin, visfatin, omentin, tumor necrosis factor-α (TNF-α), resistin, retinol-binding protein 4 (RBP4) and many others influence metabolic processes such as food intake, glucose- and lipid-metabolism, inflammation and insulin resistance." (PMID 22389718, 2012). "On regression analyses, changes in BMI predicted changes in insulin (B = 4.9 ± 2, p = 0.03), insulin resistance (B = 1.75 ± 0.65, p = 0.02) and leptin (B = 2.2 ± 1, p = 0.046) but not on ghrelin (B = 38 ± 72, p = 0.61), adiponectin (B = -0.02 ± 1, p = 0.98) or resistin (B = -0.09 ± 0.25, p = 0.74)." (PMID 21676224, 2011). "Thus, higher leptin levels in the plasma and, presumably, adipose tissue of HFD-fed WT mice may contribute to the multi-tissue insulin resistance we observe in WT vs. OPN KO mice." (PMID 21103061, 2010). "In addition, because rats chronically pretreated with leptin have normal or even improved insulin sensitivity, these data suggest that hyperinsulinemia and insulin resistance are not necessary to induce renal leptin resistance in obese animals." (PMID 21286276, 2010). "We hypothesized that the insulin resistance that is present in critical illness would affect circulating adiponectin, RBP4, and leptin levels and that the improved insulin sensitivity that we observed in intensive insulin therapy (IIT) patients would change the adipokine levels." (PMID 19589139, 2009). "Our findings support the hypothesis that sleep-disordered breathing in children with metabolic syndrome is associated with increased sympathetic nervous system activity and leptin levels but not worsening of insulin resistance." (PMID 18762497, 2008). "Notably, no other significant relationships were detected for leptin, adiponectin, or ghrelin in relation to lipid profiles, insulin resistance indicators, or fasting blood glucose levels, whether in unadjusted or adjusted models." (PMID 41423640, 2025).
Insulin resistance (continued). "In addition, the correlation between the ratio of leptin to adiponectin and systemic inflammation, as well as its ability to forecast insulin resistance among non-diabetic individuals, highlights the involvement of adipose tissue malfunction in the development of insulin resistance." (PMID 39791169, 2025). "However, when there is leptin resistance (where high levels of leptin do not operate effectively), it can result in unregulated eating and subsequent weight gain, further exacerbating insulin resistance." (PMID 37895330, 2023). "While the verification of the body weight gain has performed almost consistently, few studies have investigated whether HFD treatment produced insulin resistance, as measured by elevated fasting plasma glucose and insulin, and the measure of leptin levels has also not been routinely done." (PMID 35887310, 2022). "However, leptin-treated animals did not present alterations indicative of insulin resistance despite the chronic HF diet intake, and, in addition, they presented lower circulating leptin levels compared to the HF-Control group, all this being indicative of a healthier metabolic status." (PMID 35684076, 2022). "Likewise, some studies reported reduced leptin levels in smokers compared to nonsmokers, whereas another study suggested that nicotine may have a direct effect on insulin resistance by increasing circulating leptin levels." (PMID 36013497, 2022). "However, similar delivery of leptin to hypoleptinaemic individuals and lipodystrophic individuals with measurable quantities of circulating leptin does not affect lean mass, despite having dramatic effects on adipose mass in the former group and insulin resistance in the latter." (PMID 35844058, 2022). "However, insulin resistance may be inadequately treated by lansoprazole treatments, as the leptin level did not decrease enough in the current study." (PMID 33641315, 2021). "Therefore, leptin might be considered a pro-inflammatory cytokine given that it contributes to the ‘low-grade inflammatory state’ in T2DM patients and overweight and obese individuals with high levels of insulin resistance." (PMID 34360753, 2021). "The increase in insulin may also be as a result of insulin resistance which is also supported by the observed significant increase in TNF-α (TNF-α induces insulin resistance by inhibiting insulin signal transduction) and leptin levels (females only) in sugar fed rats compared to honey fed ones." (PMID 32153977, 2020). "In addition, the CE+BZA combination decreased serum leptin levels, leptin/adiponectin ratio, and thiobarbituric acid reactive substances in female mice, preventing fat accumulation and improved insulin resistance and glucose intolerance without stimulating uterine growth." (PMID 29802368, 2018). "The observed results support the hypothesis that adiponectin might be associated with insulin resistance and it cannot be ruled out that changes in the mean level of adiponectin per FAT mass or leptin/adiponectin ratio may precede the occurrence of insulin resistance in the future." (PMID 27212946, 2016). "Therefore, the fourth limitation is that we did not measure other cytokines, such as leptin, adiponectin, IL-6 and TNF-α, which may be related to serum irisin level and may confound the association between irisin and insulin resistance." (PMID 27473122, 2016). "Thus, there does not seem to be a relationship between variations in leptin and insulin resistance." (PMID 24198811, 2013). "Given that leptin levels are increased in MASLD patients, and leptin promotes insulin resistance, we consider the negative relationship between FGF21 and LEPR as highly suggestive for FGF21 to improve insulin sensitivity by dampening leptin signalling." (PMID 39962359, 2025).
Insulin resistance (continued). "It was proven that insulin resistance, serum total cholesterol, adiponectin, LDL-C, HDL-C, and leptin were not changed; however, fasting plasma glucose was increased by both casein and whey protein diet compositions." (PMID 38672494, 2024). "We did not measure other measures such as leptin, and assessing leptin levels would be more helpful in understanding the relationship between SCH and insulin resistance." (PMID 37484968, 2023). "High-fructose corn syrup does not elevate insulin or leptin levels as glucose does, and thus stimulates hepatic de novo lipogenesis, contributing to NASH and insulin resistance." (PMID 37233716, 2023). "Although weight, waist circumference, BMI and insulin resistance were significantly decreased, there were no significant changes in FBG and leptin concentrations." (PMID 37189189, 2023). "We see it as a limitation of our study that we do not have data on fetal insulin resistance, estrogen, IGF-1, and leptin." (PMID 35184136, 2022). "An obese rat model study showed that LWDHW decreased serum triglycerides, nonesterified fatty acid levels, body fat, serum leptin, and insulin levels, suggesting a positive effect of LWDHW in improving insulin resistance." (PMID 34457016, 2021). "Nevertheless, GSK0660 treatment notably increased serum levels of leptin, insulin, and triglyceride in rats, without affecting glucose levels, suggesting that GSK0660 induced insulin resistance in 3-month-old Wistar rats." (PMID 33924880, 2021). "Concurrently, these mice exhibited an increase in leptin, nonesterified fatty acid (NEFA), insulin, and glucose in plasma, coupled with glucose intolerance and insulin resistance." (PMID 32351670, 2020). "Independent of leptin level, serum level of TNF-α in diabetic patients correlates with the level of insulin resistance and the glucose metabolism parameters such as HbA1c." (PMID 32089876, 2020). "In the leptin- and insulin-related pathways, PTP1B and SOCS3 are negative regulators and make major contributions to leptin and insulin resistance." (PMID 31344867, 2019). "Although leptin levels were not correlated with the levels of other adipokines, leptin and MCP-1 levels were strongly correlated with the insulin resistance/sensitivity indexes." (PMID 29785210, 2018). "Exercise training decreased serum leptin, MCP-1, and resistin levels in db/db+Ex mice, but it did not reduce symptoms of insulin resistance including hyperglycemia, hyperinsulinemia, and impaired glucose tolerance." (PMID 29896118, 2018). "Although we did not observe insulin resistance in the HAM-RS2 group, it is plausible that the study participants in our study were resistant to leptin due to high blood leptin concentrations and consumption of a high-fat diet at baseline." (PMID 28222742, 2017). "Besides, we have also found that antitumor necrosis factor-α (anti-TNF-α) agents may improve insulin resistance in patients with moderate-to-severe psoriasis, although no significant changes in serum leptin or resistin concentrations after 6 months of adalimumab therapy were found." (PMID 27293954, 2016). "Lack of any correlation between leptin/TNF-α and insulin resistance in our south Asian population was an unexpected finding." (PMID 23671875, 2013). "Although obese adolescents had clear evidence of insulin resistance, only CRP, fibrinogen and leptin were elevated; there were no group differences in pro- or anti-inflammatory cytokines nor adiponectin and resistin." (PMID 22682228, 2012). "As reported, anti-inflammatory adiponectin alone was significantly lower in all PCOS patients examined, irrespective of BMI and insulin resistance, whereas in PCOS and normal healthy adults, hs-CRP and leptin were positively correlated with BMI." (PMID 21547256, 2011).